TGFBR1 (transforming growth factor beta receptor 1)
Diseases named in the same sentence as TGFBR1 in open-access papers (continued):
Sharing a sentence is not in itself a finding about the gene and the disease.
tumor (continued). "Up‐regulation of mRNA markers of inflammation and fibrosis have been previously reported in the fibrotic nontumor tissues 11, 45, as well as in tumor tissue in the present study (Tnf, Tgfβ1, Tgfbr1, and Tgfbr2)." (PMID 26778414, 2016). "As a consequence, we predicted that inhibiting TGFβ/TGFBR1 signalling would more likely be effective in preventing tumour metastasis and outgrowth of micrometastasis, rather than reducing established tumour burden." (PMID 27835901, 2016). "Since Cyp19-Cre is not expressed in the ovarian surface epithelium, our data suggest that overactivation of TGFBR1 in ovarian surface epithelial cells is not required for the observed KRT8 expression in tumor tissues." (PMID 27344183, 2016). "Since several key genes in the pathway were overexpressed in tumor tissues, including TGFB2, TGFBR1, SMAD2, and SMAD4, TGFβ signaling pathway may be involved in the pathogenesis of fibroblastic meningioma." (PMID 23285163, 2012). "Among HNPCC cases with MSI tumours (MMR/MSI positive) over-representation of TGFBR1*6A carriers was evident, albeit non-significantly compared with the controls (data not shown)." (PMID 19401691, 2009). "Further database analysis using different algorithms (TIMER2.0) revealed that TGFBR1 gene expression displayed more significant positive correlations with infiltrating macrophages than with other infiltrating immune cell types (B cells, CD8+ T cells, and CD4+ T cells) in various human tumor types." (PMID 38441961, 2024). "In our study, reduced interaction between myeloid‐derived TGFB1 and TGFBR1 in tumour foci No. 2 contributed to tumourigenesis and increased heterogeneity, which was support by the spatial‐geneset‐score and nichenet analysis, quantitate PCR and cell proliferation validation results." (PMID 38426403, 2024). "Additionally, deletion of Tgfbr1 in murine head and neck epithelia resulted in enhanced paracrine effect of TGF-β1 in tumor stroma, which facilitated the immunosuppressive status and promoted the tumor progression." (PMID 28592285, 2017). "A secondary consideration is that TGFBR1 inhibition affected proliferation of the tumour cells without inducing apoptosis, and so may not result in significant tumour shrinkage." (PMID 27835901, 2016). "Moreover, tumors from TGFBR1-CACcre ovaries were highly proliferative, expressed granulosa cell markers FOXL2 and INHA, and were immunoreactive for KRT8 during tumor progression." (PMID 27344183, 2016). "The implication of these data is that targeting TGFβ/TGFBR1 may not be an effective therapeutic strategy in established tumours." (PMID 27835901, 2016). "Seemly lower TGFB1 mRNA levels were observed in the tumours from regional lymph node-negative patients and in the triple-negative tumours, and lower TGFBR1 mRNA levels were observed in HER2 negative tumours, though the corresponding p-values did not survive Bonferroni correction." (PMID 26703884, 2015). "Furthermore, SCAND1 and MZF1 expression was negatively correlated with TGFBR1, TGFBR2, and TGFBR3 gene expression, suggesting that SCAND1-MZF1 could reduce TGFβ receptors to narrow down TGFβ signals emanating from the microenvironment to tumor cells." (PMID 36552758, 2022). "Although blocking TGFβ signaling is widely viewed as a promising anti-tumor strategy, efforts in GBM have mainly focused on blocking TGFBR1 activity without successful clinical translation." (PMID 40277917, 2025). "This knockdown significantly inhibited cell migration, though it did not affect cell proliferation or tumor growth in xenograft models, indicating that NPC1-driven migration depends on TGFBR1." (PMID 39762312, 2025). "In the tumour immune microenvironment, reduced interaction between myeloid‐derived TGFB1 and TGFBR1 in tumour focus No. 2 contributed to tumourigenesis and increased heterogeneity." (PMID 38426403, 2024).
tumor (continued). "However, deletion of a number of key TGFβ signaling components (e.g., TGFβ1, TGFBR1, SMAD2/3, and SMAD4) alone in the ovary does not induce tumor formation, challenging TGFβ signaling as essential tumor suppressor in the ovary." (PMID 27344183, 2016). "The VEGFR-1 (Vascular Endothelial Growth Factor Receptor-1), TGFBR-1 (Tumor Growth Factor β Receptor-1), TNF-R1 (Tumor Necrosis Factor Receptor-1) pathways have been reported to regulate tumor angiogenesis, but their activities have not been examined in human TEM." (PMID 25768678, 2015). "In murine skin, targeted activation of the RAS/RAF/mitogen-activated protein kinase (MAPK) pathway, coupled with deletion of Tgfbr1 in LGR5+ve stem cells, promotes rapid development of cSCC, which, in the absence of wounding, may mimic the kinetics of tumour induction in vemurafenib-induced cSCC." (PMID 27558455, 2016).
cancer (242 papers, 2003 to 2025). A tumor composed of atypical neoplastic, often pleomorphic cells that invade other tissues. "In the same context, previous studies have demonstrated that TGFBR1 acts as a potent modifier of cancer risk, and TGFBR1 overexpression has been associated with cancer cell aggressiveness and poor clinical outcomes in many malignancies." (PMID 36901700, 2023). "On the other hand, the protein levels of TGF-β, SMAD2/3, TGFBR1, and pSMAD1/5/9 in cancer stromal cells were positively associated with FOXP3+ T cell infiltration but negatively associated with CD8+ T cell infiltration." (PMID 36458816, 2022). "Multiple studies have indicated an association with polymorphisms observed in TGFBR1 and cancer susceptibility." (PMID 34068918, 2021). "A further miRNA likely involved in CRC was let-7b-5p, as it is shown implicated in modulating the TGFBR1 expression, via miRNA-mRNA binding site resulting in cancer-promoting consequences." (PMID 32992457, 2020). "And TGFBR1 involved in the transforming growth factor beta (TGF-β) signaling pathway had a significantly increased risk for cancer development." (PMID 31888623, 2019). "The loss of Tgfbr1 and Pten was shown to lead to cancer-related inflammation as well as cancer stem cell expansion in the basal epithelial layer of this model." (PMID 30917608, 2019). "The next most correlated pathway was the loss of function of TGFBR1, a protein that is important in various cancers." (PMID 31652813, 2019). "Only one EMT gene product seems to be involved in this module; TGFBR1, which has a known polymorphism that is associated with cancer development." (PMID 30115852, 2018). "We also demonstrated that TRAF6 is closely associated with EMT process and cancer stem cells using a Tgfbr1/Pten 2cKO mice SCCHN model and human SCCHN tissue microarray." (PMID 29193723, 2018). "Among these is the TGF beta receptor TGFBR1, a membrane protein receptor involved in many cancers and whose non-synonymous single-nucleotide polymorphisms were previously observed to be associated with risk for several forms of cancer, including breast." (PMID 28059167, 2017). "Stratified analysis between protective haplotype CACGA of TGFBR1 and EC risk by family history of cancer, BMI status and menarche-FFTP intervals." (PMID 27171242, 2016). "To derive a more precise estimation of the relation, we conducted a comprehensive meta-analysis of all available case-control studies relating the TGFBR1*6A and IVS7+24G>A polymorphisms of the TGFBR1 gene to the risk of cancer." (PMID 22905183, 2012). "A number of studies have investigated the association between TGFBR1 polymorphisms and cancer risk, but results are somewhat controversial and underpowered." (PMID 22905183, 2012). "Last but not least, most of US studies were mixed ethnicity, which made it hard to obtain the effects of specific ethnicity on the associations between TGFBR1 polymorphisms and cancer risk." (PMID 22905183, 2012). "For TGFBR1*6A, significantly elevated cancer risk was found in all genetic models (dominant OR = 1.11, 95% CI = 1.04∼1.18; recessive: OR = 1.36, 95% CI = 1.11∼1.66; additive: OR = 1.13, 95% CI = 1.05∼1.20)." (PMID 22905183, 2012). "Further studies regarding other SNPs (or haplotypes) in the TGFBR1 gene and cancer risk are also encouraged to better understand the role of TGFBR1 in carcinogenesis." (PMID 22905183, 2012). "Common regulatory variation affecting the expression of APC and TGFBR1 has also been shown to contribute to susceptibility to cancer in humans." (PMID 22513257, 2012). "Numerous epidemiological studies have evaluated the association between TGFBR1 polymorphisms and the risk of cancer, however, the results remain inconclusive." (PMID 22905183, 2012). "Although mutations in TGFβRI are rare, an association between the TGFBR1*6A-polymorphism and cancer has been reported." (PMID 20459617, 2010).
cancer (continued). "Boris Pasche has filed patents related to the role of constitutively decreased TGFBR1 expression as it relates to cancer risk." (PMID 20500843, 2010). "Another polymorphic variant of TGFBR1, Int7G24A, has also been implicated in cancer susceptibility, associations with kidney, bladder, breast and non-small cell lung cancer being reported." (PMID 19401691, 2009). "Functional disruption, mutation, or aberrant expression of the TGFβ type I receptor gene (Tgfbr1) is frequently associated with human diseases, including cancers." (PMID 17705854, 2007). "Germ-line predisposing or cancer-associated somatically acquired mutations are usually considered the major cause for malfunction of the Tgfbr1 gene." (PMID 17705854, 2007). "Defects in TGFBR1 gene function are associated with Loeys–Dietz aortic aneurysm syndrome, multiple self-healing squamous epitheliomas, and the development of some cancers." (PMID 37509254, 2023). "Of note, the transforming growth factor TGFBR1 is a membrane protein receptor involved in many cancers and whose polymorphisms were previously observed to be associated with risk for several forms of cancer, in particular breast cancer." (PMID 28059167, 2017). "We tested whether human cancer cells with activating mutations in MAPK pathway components were also dependent on TGFBR1 for growth." (PMID 27835901, 2016). "In conclusion, the present meta-analysis of 13 studies including 4092 cases and 5909controls suggested that Int7G24A rs334354 polymorphism of gene TGFBR1 involved inthe TGF-β signaling pathway had a significantly increased risk on therisk for cancer in both of the two genetic models." (PMID 26074400, 2015). "Moreover, a significantly increased risk was found among mixed ethnicity from US studies but not among Caucasian and Asian, and this was the first study evaluating the relation between TGFBR1 polymorphism and overall cancer risk among different populations." (PMID 22905183, 2012). "Pooled analysis of association of TGFBR1 TGFBR1*6A (rs1466445) and cancer risk." (PMID 22905183, 2012). "Characteristics of case-control studies included in TGFBR1 TGFBR1*6A polymorphism and cancer risk." (PMID 22905183, 2012). "We found that individuals with the TGFBR1*6A allele showed an increased risk of cancer." (PMID 22905183, 2012). "To derive a more precise estimation of the relationship between TGFBR1 polymorphisms and cancer risk, we carried out an updated meta-analysis of all available case–control studies relating the TGFBR1*6A and/or IVS7+24G>A polymorphisms of the TGFBR1 gene to the risk of cancer." (PMID 22905183, 2012). "TGF-β signaling may not be the same in different tissues, which might explain the tissue-related manner of the association between TGFBR1*6A genotypes and cancer development." (PMID 20429896, 2010). "Notably, a gene variant with a three-alanine deletion (Tgfbr1-6A) in the 9A stretch was found recently in a variety of cancers, suggesting that this signal peptide is a susceptible site for its gene mutation." (PMID 17705854, 2007). "Functional disruption, mutation, or aberrant expression of the Tgfbr1 gene could cause many human diseases, including cancers." (PMID 17705854, 2007). "Mutation of TGFBR1 may result in a high risk of certain cancers." (PMID 20429896, 2010). "Given its role in cancer, TGFBR1 is a therapeutic target, particularly in tumors where TGF-β signaling promotes metastasis and immunosuppression." (PMID 40725247, 2025). "The results revealed that ISCA1 CNV was positively correlated with TGFBR1 RNA expression in most cancers, and ISCA1 methylation was correlated with the RNA expression levels of these 33 immune genes in COAD, LIHC, and TGCT." (PMID 39766805, 2024). "In our study, we uncover that TSPYL1 binds the promoter of TGFBR1 in a variety of cancer cell lines as well as normal cells." (PMID 38588050, 2024).
cancer (continued). "Transforming growth factor-β receptor type 1 (TGFBR1) is a receptor for TGF-β ligands that modulates cancer stem cell properties and epithelial-mesenchymal transition." (PMID 38287071, 2024). "The correlation analysis of 24 immunosuppressants indicated that EDNRA was positively correlated with ADORA2A, CSF1R, KDR, TGFB1, and TGFBR1 in cancers, including BLCA, CHOL, ESCA, READ, and STAD." (PMID 39601333, 2024). "We observed differential expression of four genes, ALB, KIT, PDGFRB, and TGFBR1, in regular and neighbouring cancer tissues." (PMID 39364054, 2024). "We found that the abundance of either the type I (TGFBR1) or type II (TGFBR2) TGF-β receptor determined the responses of cancer cell lines, such that the receptor with relatively low abundance dictates the response." (PMID 38753874, 2024). "We further found that the protein levels of TGFβ1 and its downstream proteins, including p-TGFBR1, p-Smad2/3, Smad2-4 and the TGFβ-responsive gene SERPINE1 (encodes PAI-1), were elevated after coculturing in cancer cells." (PMID 37705745, 2023). "Here, cancer cells were treated with the TGFBR1 inhibitor SB431542, and we found that the mRNA levels of PAI-1 in B16F10-C3 and 231-GFP cells cocultured with platelets were significantly decreased by approximately 85% and 60%, respectively." (PMID 37705745, 2023). "We also noted that anti-CD47 when combined with olaparib downregulated immunosuppressive myeloid markers in cancer cells specifically, TGFBR1 and CSF1R, which has been shown to correlate with therapy resistance." (PMID 37468567, 2023). "In agreement with our results, all the studies showed that ZEB1‐circRNAs are upregulated in cancer; however, they identified different targets and functional axes (miR‐337‐3p/TGFBR1, mR‐195‐5p/LOXL2, miR‐448/EEF2K, miR‐200a‐3p/CDK6 and miR‐199a‐3p/PIK3CA)." (PMID 37408496, 2023). "Targeting TGF-β signaling in cancer has moved into clinical trials with an inhibitor of the kinase activity of the TGF-β receptor type I (TGFBR1/ALK5), Vactosertib, now in several trials, including a phase 2 trial in NSCLC (NCT04515979)." (PMID 37002229, 2023). "TGF-β/TGFbr1 is required for the effects of cancer cells on NFATc1 nuclear accumulation and osteoclastogenesis." (PMID 36593458, 2023). "The observation that knockdown of TGFBR1 led to multinucleation of cancer cells, underscores the functional role of TβRI in cytokinesis of cancer cells." (PMID 35853811, 2022). "We observed many significantly enriched interactions between the CDH12 population and fibroblasts, with the most notable being TGFBR1, CD44, and several integrins because of their involvement in cancer-associated fibroblast (CAF) activation." (PMID 34385456, 2021). "For colony-forming assay cancer cells were seeded in multi-well plates at clonal density and treated with the TGFBR1 inhibitor galunisertib and/or the AXL inhibitor." (PMID 33570712, 2021). "To better understand their role in the susceptibility and clinical features of thyroid cancer, we analyzed some TGFB1, TGFBR1, and TGFBR2 SNPs previously associated with human cancers as well as SNPs that have been implicated on gene and protein deregulation." (PMID 33905626, 2021). "PANX1 was shown to be positively associated with some immune inhibitors such as CD274, PDCD1LG2, and TGFBR1 in a variety of cancers." (PMID 34796785, 2021). "After tamoxifen (tam) induction for 10 weeks, the Tgfbr1/Pten 2cKO mice developed cancer and precancerous lesions in the oral epithelium." (PMID 32158692, 2020). "Among these putative targets, TGFBR1 was selected for further validation, as it was a widely investigated oncogene in human cancers, including HCC." (PMID 32404179, 2020). "The results revealed that both RNF38 and AHNAK were present in the cytoplasm of HCC cells, and that positive TGFBR1 staining was mainly localized in the membrane and cytoplasm of cancer cells." (PMID 30836988, 2019).